FBXO31 (F-box protein 31)
Description:
Substrate-recognition component of the SCF(FBXO31) protein ligase complex, which specifically mediates the ubiquitination of proteins amidated at their C-terminus in response to oxidative stress, leading to their degradation by the proteasome. FBXO31 specifically recognizes and binds C-terminal peptides bearing an amide: C-terminal amidation in response to oxidative stress takes place following protein fragmentation. The SCF(FBXO31) also plays a role in G1 arrest following DNA damage by mediating ubiquitination of phosphorylated cyclin-D1 (CCND1), promoting its degradation by the proteasome, resulting in G1 arrest. The SCF(FBXO31) complex is however not a major regulator of CCND1 stability during the G1/S transition (By similarity). SCF(FBXO31) complex is required for genomic integrity by catalyzing ubiquitination and degradation of cyclin-A (CCNA1 and/or CCNA2) during the G1 phase. In response to genotoxic stress, the SCF(FBXO31) complex directs ubiquitination and degradation of phosphorylated FBXO46 and MAP2K6. SCF(FBXO31) complex promotes ubiquitination and degradation of CDT1 during the G2 phase to prevent re-replication. The SCF(FBXO31) complex also mediates ubiquitination and degradation of DUSP6, OGT and PARD6A.
Synonyms: FBX14; FBX31; PP2386; FBXO14; MGC15419; MRT45
Tractability: PROTAC: UniProt records ubiquitination sites on it; ubiquitination databases record sites on it.
Gene: Protein-coding gene on chromosome 16 (87,326,987 to 87,392,142, reverse strand). Ensembl gene ENSG00000103264.
Subcellular location: Cytoplasm; Cytoplasm, cytoskeleton, microtubule organizing center, centrosome
Subcellular location (Human Protein Atlas): Nucleoplasm; Cytosol; Golgi apparatus
Pathways (Reactome):
Immune System: Antigen processing: Ubiquitination & Proteasome degradation
Metabolism of proteins: Neddylation
Gene Ontology:
Molecular function: cyclin binding; protein binding; ubiquitin-like ligase-substrate adaptor activity
Biological process: anaphase-promoting complex-dependent catabolic process; cellular response to oxidative stress; DNA damage response; mitotic G1 DNA damage checkpoint signaling; proteasome-mediated ubiquitin-dependent protein catabolic process; SCF-dependent proteasomal ubiquitin-dependent protein catabolic process; signal transduction in response to DNA damage; protein ubiquitination
Cellular component: cytoplasm; SCF ubiquitin ligase complex; cytosol; neuronal cell body; centrosome
Genetic constraint (gnomAD): Loss-of-function variants: 24 observed, 49.08 expected, observed/expected ratio (o/e) 0.49, 90% interval 0.35 to 0.69. The synonymous counts are far from expectation, so gnomAD's model fits this gene poorly and the ratio says little. Missense variants: 665 observed, 738.04 expected, observed/expected ratio (o/e) 0.9, 90% interval 0.85 to 0.96. Synonymous variants: 388 observed, 320.95 expected, observed/expected ratio (o/e) 1.21, 90% interval 1.11 to 1.32.
Homologues: Orthologues: chimpanzee FBXO31 (99% identical), macaque FBXO31 (98% identical), pig FBXO31 (90% identical), guinea pig FBXO31 (87% identical), mouse Fbxo31 (86% identical), rat Fbxo31 (85% identical), dog FBXO31 (81% identical), tropical clawed frog fbxo31 (69% identical), zebrafish fbxo31 (66% identical), rabbit FBXO31 (58% identical). Paralogues in human: FBXO39 (13% identical).
Diseases named in the same sentence as FBXO31 in open-access papers:
FBXO31 is named in the same sentence as 32 diseases in open-access papers, as found by Europe PMC text mining. Sharing a sentence is not in itself a finding about the gene and the disease. The quoted sentences say what the papers report.
breast carcinoma (5 papers, 2014 to 2023). "The E3 ligase adaptor protein FBXO31 was identified as a tumor suppressor in breast cancer and was shown to stimulate cell proliferation, invasion and metastasis in lung cancer." (PMID 36293188, 2022). "Ectopic expression of FBXO31 in breast cancer cells inhibited colony formation, cell proliferation and induced cellular senescence and G1 phase cell cycle arrest." (PMID 25115392, 2014). "The expression level of FBXO31 is relatively lower in the breast cancer and hepatocellular carcinoma tissues compared with their corresponding normal tissues." (PMID 25115392, 2014). "Our result indicated that FBXO31 was a candidate tumor suppressor in GC, which is consistent with the results in breast cancer and hepatocellular carcinoma." (PMID 25115392, 2014). "FBXO31 was initially considered as a candidate tumor suppressor since decreased FBXO31 expression was found in breast cancer." (PMID 25115392, 2014). "The results from the breast cancer and hepatocellular carcinoma indicated that ectopic expression of FBXO31 inhibited cell growth and blocks cells at G0-G1 phase of the cell cycle." (PMID 25115392, 2014).
gastric cancer (5 papers, 2014 to 2022). A primary or metastatic malignant neoplasm involving the stomach. "FBXO31 was regarded as an emerging tumor suppressor, which is often down-regulated in several human cancers, including BC, gastric cancer, and hepatocellular cancer." (PMID 30341246, 2019). "Then, we knocked down FBXO31 using FBXO31 specific siRNAs in the gastric cancer cell lines BGC-823 and HGC-27." (PMID 25115392, 2014). "Besides, overexpression of miR-20a could induce gastric cancer progression by miR-20a (miR-17)-FBXO31-CyclinD1 pathway." (PMID 30497428, 2018). "Here, we investigated the expression and prognosis value of FBXO31 in human primary gastric cancer (GC) samples." (PMID 25115392, 2014).
hepatocellular carcinoma (4 papers, 2014 to 2025). A malignant tumor that arises from hepatocytes. "Furthermore, research showed that miR-3677-3p binds to FBXO31 and inhibit its expression in hepatitis B-associated hepatocellular carcinoma, this inhibition causes FOXM1 to be less ubiquitinated and degraded, which in turn encourages the growth of HCC and sorafenib resistance." (PMID 40303979, 2025). "Decreased expression of FBXO31 was also found in hepatocellular carcinoma (HCC)." (PMID 25115392, 2014).
lung carcinoma (3 papers, 2019 to 2023). "However, overexpression of FBXO31 in lung cancer promoted cell growth and metastasis, and higher expression levels of FBXO31 predicted worse survival in esophageal squamous cell carcinoma." (PMID 30341246, 2019).
prostate carcinoma (3 papers, 2016 to 2023). A carcinoma that arises from epithelial cells of the prostate gland. "This region includes FBXO31, a key oncosuppressor in prostate cancer that commonly displays loss of heterozygosity, including in breast, ovarian and hepatocellular cancers." (PMID 27653089, 2016). "FBXO31 has been identified as a putative tumor-suppressor gene in breast, ovarian, hepatocellular, and prostate cancers." (PMID 33664230, 2021). "FBXO31, the member of protein-ubiquitin ligase, activates ERK- and suppresses PI3K-AKT-mediated signaling pathways in prostate cancer by promoting the degradation of DUSP6." (PMID 36688696, 2023).
Intellectual disability (2 papers, 2022 to 2025). "Loss of function mutations in FBXO31 cause recessive intellectual disability." (PMID 39880951, 2025). "The previously reported work proposed that a frameshift variant in the FBXO31 gene causes mild‐to‐moderate intellectual disability and facial dysmorphisms such as broad nasal bridge, fleshy nares, thick eyebrows, and coarse faces in a family diagnosed with ID from Pakistan." (PMID 35019165, 2022). "Using WES, we found two novel homozygous variants in FBXO31 and TIMM50 genes in four Iranian consanguineous families diagnosed with autosomal recessive neurodevelopmental disorders with intellectual disability." (PMID 35019165, 2022).
pancreatic cancer (2 papers, 2024 to 2025). "Additionally, some research has demonstrated that FBXO31 functions as an oncoprotein that facilitates the development and spread of pancreatic cancer." (PMID 40822976, 2025).
adrenal tumors (1 paper, 2022). "They assessed in the perirenal region of PPGL higher expression of UCP1, CIDEA, ELOVL3, EBF3, FBXO31 and LHX8, but not TNFSRF9, TBX1 or TMEM26, in comparison with seven subjects with non-functional adrenal tumors." (PMID 35327387, 2022).
atrial fibrillation (1 paper, 2025). A disorder characterized by an electrocardiographic finding of a supraventricular arrhythmia characterized by the replacement of consistent P waves by rapid oscillations or fibrillatory waves that vary in size, shape and timing and are accompanied by an irregular ventricular response. "The WMH TWAS also identified genes associated with AD (ARMS2), atrial fibrillation (NEURL and GJC1), innate immunity (EFTUD2), and apoptosis and neurodevelopment (PDCD7, FBXO31, and ClpX)." (PMID 40141087, 2025).
bile duct cancer (1 paper, 2024). "The presence of F-Box Protein 31(FBXO31) enhances the cytotoxic effects of cisplatin in bile duct cancer cells by promoting iron-dependent cell death." (PMID 38650929, 2024).
breast tumor (1 paper, 2021). "High-regulation of FBXO31 inhibits the proliferation and colony formation of breast tumor cells by mediating ubiquitination and degradation of specific substrates, and then inhibits cancer progression." (PMID 33622332, 2021).
Cachexia (1 paper, 2019). Severe weight loss, wasting of muscle, loss of appetite, and general debility related to a chronic disease. "To further validate cachexia development using established molecular markers of muscle wasting, we examined the expression of genes that encode ubiquitin ligases associated with muscle proteolysis (Trim63/MuRF1, Fbxo32/MAFBx, Fbxo31, Fbxo30/Musa1)." (PMID 31861290, 2019).
glioma (1 paper, 2025). A benign or malignant brain and spinal cord tumor that arises from glial cells (astrocytes, oligodendrocytes, ependymal cells). "Additionally, overexpression of FBXO31 leads to reduced lipogenesis by inhibiting the activation of the AKT/mTOR signaling axis, thus preventing tumor growth and invasiveness in gliomas." (PMID 39944823, 2025).
melanoma (1 paper, 2025). A malignant, usually aggressive tumor composed of atypical, neoplastic melanocytes. "In melanoma cells, FBXO31 causes cell cycle arrest and prevents tumor growth in vivo." (PMID 40822976, 2025). "Analysis of the TCGA database showed that FBXO31 expression is reduced in melanoma tissues compared to normal tissues." (PMID 40822976, 2025). "Further investigations are warranted to explore the relationship between FBXO31, tumor metabolism, and drug resistance in melanoma." (PMID 40822976, 2025). "The purpose of this study was to illustrate how FBXO31 affects the stemness, invasion, and migratory properties of melanoma stem cells." (PMID 40822976, 2025). "In this study, we demonstrate for the first time that FBXO31 expression is significantly downregulated in melanoma SP cells." (PMID 40822976, 2025). "All these findings collectively suggest that FBXO31 attenuates the stemness features of CD147 (+) melanoma stem cells." (PMID 40822976, 2025). "Overall, FBXO31 inhibits the migration, invasion, and stemness characteristics of CD147 (+) melanoma stem cells." (PMID 40822976, 2025).
muscle atrophy (1 paper, 2024). The loss of muscle tissue due to inactivity or disease. "Furthermore, the mRNA levels of ubiquitin ligases [e.g., Atrogin‐1, muscle ubiquitin ligase of SCF complex in atrophy‐1 (i.e., MUSA1) and F‐box protein 31 (i.e., Fbxo31)], which are known to induce muscle atrophy, were increased in the DEX‐treated cells, and KLF13 knockout augmented these effects." (PMID 38973459, 2024).
ovarian disorder (1 paper, 2024). A disease involving the ovary. "Given the predominant role of FBXO31 in regulating cell survival, we reasonably infer its involvement in follicular atresia and the occurrence of ovarian disorders." (PMID 37611899, 2024). "However, FBXO31, one of the predicted targets of miR-106a-5p, has not yet been investigated in the pathology of ovarian disorders." (PMID 37611899, 2024).
pancreatic adenocarcinoma (1 paper, 2024). "To investigated the expression profile of FBXO31 in pancreatic adenocarcinoma (PAAD), which constitutes 90–95% of PC, we analyzed TCGA and GTEx clinical datasets, including 179 cases of PAAD tissues and 171 cases of adjacent normal tissues (167 cases from GTEx and 4 cases from TCGA)." (PMID 38216561, 2024).
schizophrenia (1 paper, 2013). A major psychotic disorder characterized by abnormalities in the perception or expression of reality. "Hence, it will be highly informative to determine how systemic or conditional deletions of FBXO31 affect brain development and if defects and phenotypes resulting thereof are reminiscent of developmental brain disorders including schizophrenia." (PMID 23469015, 2013). "Interestingly, a recent report revealed a drop in FBXO31 levels in schizophrenic patients with short term illness, implicating FBXO31 in schizophrenia." (PMID 23469015, 2013).
Sepsis (1 paper, 2025). Sepsis is defined as life-threatening organ dysfunction caused by a dysregulated host response to infection. "Given the central role of oxidative stress in sepsis pathogenesis, we hypothesize that FBXO31 may contribute to immune regulation during sepsis by maintaining proteostasis in immune cells." (PMID 41194984, 2025). "In the GSE65682 sepsis dataset, these genes showed high discriminative ability, with AUC values reaching 0.970 (CDC25B), 0.965 (FBXO31), and 0.967 (PTCD3)." (PMID 41194984, 2025). "Differential gene expression and co-expression network analyses identified five key genes—CDC25B, DPP7, FBXO31, PTCD3, and CNPY2—that play critical roles in immune response and cellular regulation in sepsis and T2DM." (PMID 41194984, 2025). "In conclusion, our study indicates the potential importance of key genes including CDC25B, DPP7, FBXO31, and PTCD3 in the shared pathogenesis of sepsis and T2DM." (PMID 41194984, 2025). "Further refinement by intersecting these genes with previously identified DEGs yielded five candidate genes: CDC25B, DPP7, FBXO31, PTCD3, and CNPY2, These genes emerged as promising biomarkers for both T2DM and sepsis, warranting further investigation into their functional roles." (PMID 41194984, 2025). "Related patterns were observed for FBXO31, PTCD3, and CNPY2, which also demonstrated significant correlations with multiple immune cell subsets, underscoring their collective involvement in sepsis immunopathology." (PMID 41194984, 2025).
skin melanoma (1 paper, 2025). "Clinical skin melanoma tissue samples were not collected to validate the expression levels of FBXO31 and CD147." (PMID 40822976, 2025).
tumor (18 papers, 2008 to 2025). "Our previous studies demonstrated that FBXO31 functions as a tumor suppressor in GC by targeting several important oncoproteins, such as CyclinD1, Snail1, and the loss of FBXO31 protein is associated with a higher malignant phenotype and poorer prognosis." (PMID 35338113, 2022). "They found that the expression level of FBXO31 was positively associated with tumor invasion depth and clinical stage." (PMID 25115392, 2014). "Univariate Cox regression analyses indicated that tumor size (P=0.016), depth of tumor infiltration (P=0.044), local lymph node metastasis (P<0.001) and FBXO31 expression (P=0.004) were significantly associated with patients' survival." (PMID 25115392, 2014). "FBXO31 expression was significantly associated with tumor size, tumor infiltration, clinical grade and patients' prognosis." (PMID 25115392, 2014). "The E3 ligase FBXO31-SCF has previously been implicated in cell cycle regulation as it emerged as a tumor suppressor and regulator of DNA repair by degrading cyclin D1." (PMID 23469015, 2013). "Therefore, the opposite role of FBXO31 in different human cancers was critically associated with its downstream substrates, acting as oncogenic or tumor suppressive role." (PMID 38216561, 2024). "FBXO31 was identified as a tumor suppressor in breast cancer and prostate cancers and it located at chromosome 16q24.3 loss of heterozygosity region." (PMID 38216561, 2024). "IHC data of tissue microarray showed that cytoplasmic FBXO31 expression levels were up-regulated in tumor tissues compared to their adjacent normal tissues (p < 0.001)." (PMID 38216561, 2024). "FBXO31 has been frequently suggested to function as tumor suppressor or oncogenic gene in different tumors." (PMID 38216561, 2024). "In fact, a number of these cullins-associated E3 ligases, such as Fbxo31, Keap1, DDB2, and the cullins, have been demonstrated to function as tumor suppressors or components of tumor suppressor complexes." (PMID 37943017, 2023). "Interestingly, genes encoding ubiquitin ligases (Trim63, Fbxo32/MAFBx, Fbxo31, and Fbxo30/Musa1) that target muscle proteins and serve as markers of muscle atrophy were found to be transcriptionally upregulated in the gastrocnemius muscles from the tumor‐bearing mice." (PMID 32730698, 2020). "Overexpression of FBXO31 in cancer cells inhibited cell growth and colon formation, and ectopic expression of FBXO31 significantly decreased tumor formation in xenograft nude mice." (PMID 30341246, 2019). "Since FBXO31 was markedly down-regulated in GC samples and played a very important role in inducing G1 phase arrest and inhibiting tumor formation in vivo, we next sought to explore the molecular mechanism leading to the down-regulation of FBXO31 in GC." (PMID 25115392, 2014). "The Cyclin D1 expression level was low in the tumor samples of FBXO31 overexpression group, which was similar with what we observed in vitro." (PMID 25115392, 2014). "Collectively, our data demonstrated that FBXO31,a member of F-box family, exerts tumor-suppressive function in GC." (PMID 25115392, 2014). "Numerous malignancies exhibit low levels of FBXO31 expression, and FBXO31 can hinder tumor growth." (PMID 40822976, 2025). "Western blotting data showed the high expression of FBXO31 in tumor tissues." (PMID 38216561, 2024). "We found that FBXO31 overexpression enhanced tumor mass size, weights and volumes." (PMID 38216561, 2024). "FBXO31 promoted cell viability and motility in vitro and enhanced tumor growth in vivo." (PMID 38216561, 2024). "Consistently, FBXO31 overexpression promoted tumor growth in nude mice." (PMID 38216561, 2024). "Future studies may be needed to develop new small molecular compounds to destroy the interaction of STYX with FBXO31, thereby recovering the tumor suppressor effects of FBXO31 in GC." (PMID 35338113, 2022). "Maybe FBXO31 didn’t function as a tumor suppressor, the mechanism of action in BC still need to further explore." (PMID 33622332, 2021).